BRAF (B-Raf proto-oncogene, serine/threonine kinase)
Diseases named in the same sentence as BRAF in open-access papers (continued):
Sharing a sentence is not in itself a finding about the gene and the disease.
melanoma (continued). "For example, BRAF mutations, prevalent in approximately 50% of human melanomas, are less frequent in canine melanomas, occurring in ~6% of cases." (PMID 41394861, 2025). "Mutations of the BRAF (B-Raf, B-rapidly accelerated fibrosarcoma) serine-threonine kinase are associated with poor prognoses in melanoma, colorectal cancer (CRC), non-small cell lung cancer (NSCLC), and other cancers." (PMID 39935431, 2025). "One, located in the head and neck area, showed 100% spitzoid morphology and immunohistochemical reactivity for BRAF V600E, therefore being classified as a spitzoid BRAF-mutated melanoma." (PMID 40851494, 2025). "Translational and retrospective data suggest that patients with advanced-stage melanoma and BRAF V600K mutations derive a greater benefit from ICI therapy than BRAF-targeted therapy." (PMID 39550033, 2025). "In one study, 161 stage II–III high-risk resected melanoma patients treated with adjuvant bevacizumab versus (vs.)placebo within the AVAST-M clinical trial were studied with ddPCR to detect BRAF and NRAS common mutations in plasma." (PMID 39859576, 2025). "Trametinib is a MEK1 and MEK2 inhibitor that is mainly used for melanoma with BRAF V600E or V600K mutations in clinical practice." (PMID 41311737, 2025). "Ravoxertinib, an inhibitor of extracellular signal-regulated kinase (ERK) with potential antineoplastic activity, has been approved by the FDA to treat melanoma patients with BRAF V600E mutation." (PMID 40761343, 2025). "Another study showed that combined PD-1, BRAF and MEK inhibition was associated with an ORR of 78% in advanced BRAF-mutant melanoma." (PMID 41225509, 2025). "BRAF mutations have been identified in approximately 5% of all malignancies, with the highest incidence observed in melanoma (39.7%), thyroid cancer (33.3%), small intestinal malignancies (8.9%), and non‐small cell lung cancer (NSCLC) (2%–5%)." (PMID 39950095, 2025). "Approximately 50% of melanomas harbor a BRAF mutation, with the most common being V600E, followed by V600K and other less frequent variants." (PMID 40758471, 2025). "Given the essential roles of mutant BRAF in melanoma initiation, drugs targeting BRAF mutation were developed and bring great benefits to patients with unresectable and metastatic melanoma, such as Vemurafenib." (PMID 41145465, 2025). "Combined BRAF/MEK inhibition has become the standard of care for melanomas with BRAF mutations, but improvements are necessary to combat acquired resistance." (PMID 40564107, 2025). "While our sample size was limited, this is, to our knowledge, the first Chilean study to report on BRAF mutation prevalence and clinical correlations in melanoma." (PMID 40994966, 2025). "Our study primarily focused on melanoma cell lines with specific genetic backgrounds, particularly those harboring a BRAF V600D mutation." (PMID 39948552, 2025). "The MAPK pathway has a crucial role in melanoma pathogenesis and is activated by mutations in the key signalling pathway members, including BRAF, NRAS, NF1 and KIT." (PMID 41017066, 2025). "Binimetinib is a drug originally approved for the treatment of malignant melanoma harboring the BRAF V600 mutation in combination with encorafenib, as well as non-small cell lung cancer." (PMID 41373567, 2025). "For example, a study demonstrated that the loss of PTEN leads to resistance to BRAF inhibitors in melanoma cells by suppressing the expression of BIM." (PMID 40129883, 2025). "Targeted BRAF inhibitors (BRAFi) such as vemurafenib and dabrafenib are vital therapeutic options for melanoma patients carrying BRAF V600E mutation and demonstrate significant therapeutic efficacy." (PMID 41198656, 2025). "In melanoma, the BRAF p.V600E mutation has been a critical target, with inhibitors such as vemurafenib demonstrating substantial clinical activity." (PMID 40869045, 2025).
melanoma (continued). "The most common BRAF mutation is V600E, which accounts for approximately 90% of BRAF mutations found in melanoma." (PMID 40793752, 2025). "This mutation is a common hotspot in BRAF and has been reported in various cancers, including melanoma, lung cancer, and colorectal cancer." (PMID 40492122, 2025). "Nearly 66 percent of cases with melanoma harbor a BRAF mutation at codon 600 with most of these patients having a V600E mutation while the remaining cases are BRAF wild type (WT) or harbor a BRAF non-V600E mutation." (PMID 39940799, 2025). "Melanoma cell lines with BRAF^V600E and BRAF^V600K mutations exhibited enhanced tumor cell killing and decreased cell viability when CX-4945, a selective CK2 inhibitor, was used with vemurafenib." (PMID 40508214, 2025). "BRAF inhibitors (BRAFi) and MEK inhibitors (MEKi) consitute a pharmacological combination that has received approval from the Food and Drug Administration (FDA) for the treatment of patients diagnosed with BRAF-mutated melanoma." (PMID 40497999, 2025). "Among these concordant pairs, the proportion of BRAF V600E-mutated cells was comparable in melanoma and nevus in 39% (9/23) of cases, whereas in 48% (11/23), the melanoma harbored a higher percentage of mutant cells compared with the adjacent nevus." (PMID 41375060, 2025). "Oncogenic mutations in BRAF are common in 50% of melanomas establishing intrinsic resistance linked to constitutive activation of the BRAF/MEK/ERK signaling pathway and leading to uncontrolled cell proliferation." (PMID 40076912, 2025). "Genetic mutations in KRAS, NRAS, and BRAF were commonly implicated in the development of both melanoma and CRC, while mutations in CDKN2A and BRCA2 were specifically significant in melanoma." (PMID 40447784, 2025). "BRAF mutations are found in approximately 4–8% of all cancers, with the highest prevalence in melanoma, thyroid cancer, colorectal cancer (CRC), and non-small cell lung cancer (NSCLC)." (PMID 41368991, 2025). "Approximately 70–80% of melanocytic nevi and ∼50% of malignant melanomas harbor mutations in the BRAF gene, with BRAFV600E being the most prevalent alteration." (PMID 40719625, 2025). "Approximately 50% of melanomas carry activating BRAF mutations, with over 90% being the V600E variant." (PMID 39934865, 2025). "Therapies can counteract the molecular defects present in melanoma, among which the most effective are BRAF inhibitors, which are used to treat metastatic and unresectable BRAF-mutated melanoma." (PMID 40932870, 2025). "The molecular diagnosis of melanoma is based on the identification of BRAF-mutant tumors, but only BRAF V600E/K mutations are of therapeutic relevance." (PMID 40361349, 2025). "This is significant because TERT promoter mutations are present in 30–85% of melanomas, including up to half of BRAF wt cases." (PMID 39859576, 2025). "Results from a recently published phase 1/2 multicenter clinical trial showed that the combination therapy of Dabrafenib, trametinib, and the autophagy inhibitor hydroxychloroquine was safe and effective in patients with BRAF-mutated melanoma." (PMID 41155168, 2025). "This delivery system improves the targeting and internalization of siRNA into melanoma cells while improving the gene silencing efficiency for the mutant BRAF gene associated with this type of cancer." (PMID 40277680, 2025). "The presence of the BRAF V600E mutant variant in melanoma is associated with several clinical characteristics." (PMID 40507250, 2025). "Medications like vemurafenib and dabrafenib target the BRAF (V600E) mutation and have shown improved OS in clinical trials, and they are often used as first-line treatments for metastatic BRAF-mutant melanoma." (PMID 40867277, 2025). "Accurate diagnosis of dedifferentiated melanoma demands a high level of suspicion and comprehensive sampling to identify either a conventional melanoma precursor or mutations consistent with melanoma, such as BRAF, NRAS, or NF1." (PMID 39625060, 2025).
melanoma (continued). "Nanoparticles modified with sulfates, such as BRAF-mutated melanomas and BRCA-mutated breast cancers, have been developed to actively target P-selectin-expressing cancers." (PMID 40723245, 2025). "Melanoma cells with BRAF mutation not only increase glycolytic activity but also modify how they absorb and utilize glucose." (PMID 40872623, 2025). "Approximately 50% of melanomas harbour activating mutations of BRAF, with the V600E variant being the most common." (PMID 40690563, 2025). "Class I BRAF mutations, specifically BRAF V600E, are strongly associated with tumors such as melanoma, colorectal cancer and thyroid cancer." (PMID 40977811, 2025). "A 25-year-old male with BRAF V600E mutation-positive malignant melanoma of the right eyebrow underwent a wide local excision and sentinel lymph node biopsy." (PMID 41487768, 2025). "The aim of this study was to synthesize new telmisartan–amino acid conjugates that lack antihypertensive activity, and to investigate their anticancer potential against BRAF V600-mutated melanoma cells." (PMID 41515422, 2025). "The genes most frequently associated with melanoma pathogenesis include BRAF, NRAS, neurofibromin 1 (NF1), and KIT." (PMID 39859576, 2025). "Our findings indicate that ALDH2 downregulation contributes to melanoma progression and therapy resistance in BRAF-mutated human metastatic melanoma cells, highlighting ALDH2 as a potential prognostic marker and therapeutic target in metastatic melanoma." (PMID 40558540, 2025). "The use of BRAF and MEK inhibitors is more limited, given that BRAF mutations are present in approximately 50% of patients diagnosed with melanoma." (PMID 40868149, 2025). "BRAF mutation was more frequently observed in ulcerated melanoma (16/23; 69.6%), with mitotic rate ≥ 5 n/mm2 (8/11; 72.7%), while NRAS mutation was more common in amelanotic/hypomelanotic (8/17; 70.0%) and nodular melanoma (10/24; 41.7%)." (PMID 40867317, 2025). "BRAF-mutated melanoma was significantly associated with the presence of shiny white structures (OR = 3.50, 95% CI: 1.13–10.84; p = 0.030)." (PMID 40867317, 2025). "Among them, SRC activation has been implicated in resistance to drugs targeting the MAPK pathway, including EGFRi in KRAS-mutated CRC or BRAFi in BRAF-mutated melanoma." (PMID 40481178, 2025). "These drugs act through checkpoint inhibition and targeted proliferation arrest in melanomas with BRAF mutation." (PMID 40868208, 2025). "In melanoma, mutations in BRAF V600 (present in 40–60% of patients) or NRAS Q61 (found in about 25%) make these methods particularly effective for analyzing ctDNA in most cases." (PMID 39859576, 2025). "P90 ribosomal S6 kinase (RSK), a major MAPK substrate, is necessary to maintain glycolysis metabolism in BRAF-mutated melanoma." (PMID 40617808, 2025). "Prospective phase III trials show worse PFS for patients with a BRAF mutation and advanced melanoma treated with anti‐PD1 monotherapy when compared to their BRAF WT counterparts." (PMID 41342263, 2025). "Melanoma, the most lethal form of skin cancer, is commonly associated with mutations in the BRAF gene, particularly BRAFV600E, which drives tumor proliferation via the ERK1/2 signaling cascade." (PMID 40719625, 2025). "Targeted therapies have drastically improved survival for patients with advanced, BRAF-mutated melanoma, especially when compared to traditional chemotherapy." (PMID 40564107, 2025). "Their cytotoxicity was tested on BRAF V600E-mutated melanoma cell lines (A375 and 518A2), and compounds 1, 3, and 8 stood out as the best candidates." (PMID 41515422, 2025). "On one hand, common genetic mutations in melanoma, such as BRAF, NRAS, and NF1, result in multiple potential resistance pathways within the MAPK signaling axis." (PMID 40599859, 2025). "The RAS/RAF/MAPK/ERK signaling pathway is predominantly activated in melanomas through NRAS or BRAF mutations." (PMID 40331942, 2025).
melanoma (continued). "Mutations in the NRAS GTPase are the second most common mutation noted in melanoma after BRAF, observed in 15–20% of melanomas." (PMID 39859464, 2025). "The identification of patients at high risk of melanoma-related death based on their BRAF genotype can inform recommendations for treatment, follow-up and eligibility for adjuvant trials." (PMID 40902091, 2025). "This study identifies a novel oncogene, TRIM63, and elucidates its functional mechanisms that drive melanoma progression associated with BRAF mutations commonly observed in melanoma." (PMID 41315179, 2025). "A relevant limitation of this study in the context of melanoma research is that the studied cells, A375, have the homozygous BRAF V600E mutation." (PMID 41304533, 2025). "Aside from the differences in testing methods and sensitivity levels, a literature review demonstrates that NRAS and BRAF mutations are mutually exclusive in melanoma." (PMID 39940799, 2025). "Like KRAS mutations, BRAF can be present in both cancers but appears to be more prevalent in melanoma development than in CRC development." (PMID 40447784, 2025). "Background/objectives: Melanoma is one of the deadliest forms of malignant cancers; ultraviolet radiation exposure together with genetic mutations, such as BRAF, represent the main risk factors and are involved in metastatic dissemination." (PMID 40868208, 2025). "Here we combined the H2B-GFP label-retention system and a surface marker approach to isolate and extensively characterize in vitro and in vivo quiescent cells in our NRAS or BRAF mutated human melanoma PDXs." (PMID 40528051, 2025). "The proline 29 to serine (P29S) mutation in RAC1 is the third most common hotspot mutation in melanoma, following BRAF V600E and neuroblastoma RAS viral oncogene homolog (NRAS) Q61R." (PMID 41034404, 2025). "Melanoma CSCs often harbor mutations in such genes as BRAF and NRAS, which are associated with resistance mechanisms, including the reactivation of mitogen-activated protein kinases (MAPK) signaling pathways." (PMID 40867277, 2025). "The BRAF gene mutation (the most common is V600E) can be found in almost 50% of melanoma cases and represents a relevant therapeutic target." (PMID 40332507, 2025). "In most cases, melanoma develops from ultraviolet (UV)-damaged melanocytes that acquire multiple mutations in proliferation-associated genes, such as BRAF or NRAS13." (PMID 40562773, 2025). "BRAF V600E mutations are present in approximately 50% of melanomas and hyperactivate the MEK-ERK1/2 signaling pathway." (PMID 41193428, 2025). "Mutations in the BRAF gene are implicated in the development of cancers, such as melanoma and colorectal, as these mutations lead to hyperactivation of BRAF kinase and unchecked cellular proliferation." (PMID 39839461, 2025). "In the present study, patients with BRAF-mutated melanomas were younger than those with BRAFWT melanomas, a finding consistent with other studies." (PMID 41010758, 2025). "Melanoma also has BRAF mutations, and clinical trials have been conducted to test the effects of BRAF inhibitors." (PMID 40290312, 2025). "A retrospective study analyzed 683 patients with advanced BRAF-mutated melanoma treated with first-line immunotherapy or targeted therapy; the authors evaluated brain metastasis-free survival, OS, incidence of brain metastases, and sequencing strategies." (PMID 40332507, 2025). "The V600E mutation, predominant in 80% of BRAF-related melanomas, is often found in younger patients at anatomical sites shielded from sun exposure." (PMID 38891988, 2024). "This relationship, explored in colorectal cancer, suggests the potential for microbiota profiles as biomarkers and therapeutic targets in BRAF-mutated cancers, though evidence in melanoma is limited." (PMID 38474231, 2024). "BRAF mutations are prevalent in melanomas, primarily in trunk locations, and targeted therapies have shown clinical responses." (PMID 38534309, 2024).
melanoma (continued). "The MDA-MB-435 and SK-MEL-5 melanoma cells lines are known to harbor BRAF Val600Glu (V600E) mutations and to be sensitive to the BRAF inhibitor vemurafenib." (PMID 38540310, 2024). "When combined treatment is not possible or after the failure of BRAF and MEK inhibitors in BRAF-mutated melanomas, approximately 75% of patients treated with monotherapy with iPD-1 undergo progression within 5 years." (PMID 39410017, 2024). "Previously, BRAF mutations were shown to be associated with younger age and melanoma location at sun-shielded skin sites." (PMID 39735251, 2024). "In conclusion, we unveil that the distinct regulatory patterns of laminB1 on apoptosis and autophagy cooperatively contribute to the BRAFi resistance in BRAF-mutated melanoma cells, implying the potential of laminB1 in promoting efficacy of targeted therapies." (PMID 39682248, 2024). "The oncogene HRAS, rather than NRAS and KRAS, is mutated in cSCCs, particularly in cSCCs occurring in melanoma patients treated with BRAF inhibitors (3–20%), and it promotes the upregulation of downstream MAPK and PI3K/AKT/mTOR signaling." (PMID 39201498, 2024). "BRAF inhibitors, such as vemurafenib, have been proven as effective for melanomas with BRAF V600 mutations but often come with a shorter duration of response and the potential for developing resistance." (PMID 39529955, 2024). "Inhibition of caspase activity with the pan-caspase inhibitor Z-VAD-FMK completely mitigated the super-additive cytotoxicity effect and the induction of sub-G1 cells caused by CuET with trametinib in the BRAF WT melanoma cell lines." (PMID 38263136, 2024). "Approximately 45–50% of all melanomas harbor activating mutations in the BRAF gene of the MAPK signaling pathway." (PMID 39519404, 2024). "BRAF-mutated melanoma presents different clinical features and a more aggressive biological behavior, with a greater tendency to present distant metastases and brain lesions." (PMID 38450188, 2024). "We established two BRAF-mutated melanoma cell lines (WM115 and WM164) with PLX4720-resistance to further validate the correlation between the laminB1 expression and the response to PLX4720." (PMID 39682248, 2024). "We observed a high frequency of TERT promoter mutations in AYA melanomas that showed a trend of co-occurrence with BRAF mutations, similar to findings in older adult patients which potentially suggests an intrinsic pathway of immunosuppression." (PMID 38589406, 2024). "The BRAF V600E mutation was successfully detected in 88.9% of SKMEL28 tumor cells tested with the UltraSEEK® Melanoma Panel." (PMID 38898234, 2024). "The BRAF V600E mutation is the most common melanoma-related mutation, leading to constitutive activation of the B-Raf kinase, resulting in uncontrolled cell proliferation and tumor formation." (PMID 39581873, 2024). "Demonstrating impressive diagnostic performance, PLA1A effectively distinguishes BRAF-mutated melanoma samples with a sensitivity of 62% and specificity of 61%." (PMID 39582535, 2024). "Sequence analysis of mutations in the melanomas revealed that increased susceptibility to VSV infection correlated with mutations in BRAF, which is part of the RAS/MAPK pathway that controls cell growth, division, differentiation, movement, and apoptosis." (PMID 39861805, 2024). "Improvements are particularly notable in melanoma, especially in the setting of BRAF-V600E and BRAF-V600K mutations, which represent 40-50% of metastatic melanoma cases and are amenable to targeted therapies (TT) with BRAF/MEK inhibitors (BRAF/MEKi)." (PMID 39502313, 2024). "Given the promising clinical outcomes observed with BRAF inhibitor (BRAFi) therapy in BRAF-mutated melanoma, we directed our initial focus to the dose–response profiles associated with inhibitor compounds targeting the BRAF kinase within the ERK/MAPK pathway." (PMID 39304771, 2024). "HMGCL was shown to be increased in androgen-free prostate cancer cells and BRAF-mutated melanoma cells." (PMID 38551020, 2024).